MEIS1 (Meis homeobox 1)
Diseases named in the same sentence as MEIS1 in open-access papers (continued):
Sharing a sentence is not in itself a finding about the gene and the disease.
myocardial infarction (5 papers, 2016 to 2025). Gross necrosis of the myocardium, as a result of interruption of the blood supply to the area, as in coronary thrombosis. "Double knockout of Meis1 and Hoxb13 (Homeobox B13), a cofactor of Meis1, reactivates cell cycle activity in adult cardiomyocytes, induces sarcomere disassembly and improves cardiac function following myocardial infarction." (PMID 34692797, 2021).
Nephroblastoma (5 papers, 2014 to 2023). An embryonal neoplasm characterized by the presence of epithelial, mesenchymal, and blastema components. "Additionally, we found an inverse correlation of miR-204 and the oncogenic transcription factor Meis homeobox 1 (MEIS1), which is consistent with a previous study showing a downregulation of miR-204 and an overexpression of MEIS1 in a high proportion of Wilms tumors." (PMID 27043538, 2016). "There was research which found that MEIS1 and PBX2 overexpressed in nephroblastomas." (PMID 36836180, 2023). "Recent publications provided clues that MEIS1 may participate in tumor progression, including leukemogenesis, NSCLC or nephroblastoma progression." (PMID 28270206, 2017).
non-small cell lung carcinoma (5 papers, 2017 to 2022). A group of at least three distinct histological types of lung cancer, including non-small cell squamous cell carcinoma, adenocarcinoma, and large cell carcinoma. "Similar studies reported that MEIS-1 is a suppressor of non-small-cell lung cancer, esophageal squamous cell carcinomas and clear cell renal cell carcinomas." (PMID 29632641, 2018). "MEIS1 inhibits non-small cell lung cancer cell proliferation." (PMID 33711952, 2021).
clear cell renal cell carcinoma (4 papers, 2017 to 2025). "Studies have suggested that MEIS1 may function as a tumor suppressor in the progression of clear cell renal cell carcinoma (ccRCC), since the endogenous expression of Meis1 is reduced in ccRCC cell lines." (PMID 33402862, 2020). "MEIS1 was overexpressed via adenovirus vector in clear cell renal cell carcinoma (ccRCC) cells." (PMID 28270206, 2017). "By investigating the role of MEIS1 in ccRCC cells’ survival, proliferation, anchorage-independent growth, cell cycle progress, apoptosis and metastasis, in the present work, we propose that MEIS1 may play an important role in clear cell renal cell carcinoma (ccRCC) development." (PMID 28270206, 2017). "MEIS1 was downregulated in most tumors, and high MEIS1 expression predicted better OS in patients with HNSCC, adrenocortical carcinoma, and clear cell renal carcinoma." (PMID 39910672, 2025).
esophageal squamous cell carcinoma (4 papers, 2018 to 2021). Esophageal squamous cell carcinoma (ESCC) is a type of esophageal carcinoma (EC) that can affect any part of the esophagus, but is usually located in the upper or middle third. "In addition, it has been recently reported that MEIS1 may have cancer stemness property in esophageal squamous cell carcinoma (ESCC) where its downregulation was inversely correlated with stage of progression and metastasis of the tumor." (PMID 31090196, 2019). "Few studies have established pluripotency and self-renewal regulatory roles for MEIS1 in human esophageal squamous cell carcinoma (ESCC), and our aim in this study was to evaluate the functional correlation between MEIS1 and the stemness markers in ESCC patients and cell line KYSE-30." (PMID 32819319, 2020).
migraine (4 papers, 2020 to 2025). "Previous GWASs have identified six RLS risk loci (MEIS1, BTBD9, MAP2K5, PTPRD, TOX3, and an intergenic region on chromosome 2p14); however, only MEIS1 has been found to be associated with RLS in patients with migraine via candidate gene approach." (PMID 35350973, 2022). "A recent genome-wide analysis revealed two novel loci associated with RLS in patients with migraine in addition to six previously identified RLS risk loci, namely, MEIS1, BTBD9 and PTPRD." (PMID 39801933, 2025). "We previously identified that a single-nucleotide polymorphism (SNP) rs2300478 at MEIS1, the gene responsible for iron homeostasis, increased the risk of RLS by 1.42-fold in migraine subjects via a candidate gene approach." (PMID 35350973, 2022). "In the replication part of our study, three SNPs at RLS risk loci (MEIS1, PTPRD, and an intergenic region on chromosome 2p14) were genotyped in 233 patients with migraine and in 53 with comorbid RLS." (PMID 32918390, 2020). "In the replication portion of the study, we found that two SNPs (rs2300478 in MEIS1 and rs4626664 in PTPRD) increased the risk of RLS in the migraine cohort but only rs4626664 in PTPRD increased the risk of RLS in individuals with MoA." (PMID 32918390, 2020).
prostate tumors (4 papers, 2013 to 2020). "In summary, our analysis of MYC-expressing prostate tumors demonstrates an inverse relationship with MEIS1 expression, which in turn is negatively correlated with HOXB13 expression and AR activity." (PMID 32681068, 2020). "Similar to FZD7, we found MEIS1 is down-regulated in both prostate tumors and PCa cell lines, and a high MEIS1 expression is an indication of better overall survival for PCa patients." (PMID 29416676, 2018). "The role of MEIS2 and MEIS1 in low-grade prostate tumors suggests that they play a critical function in the formation of poor prognosis." (PMID 24391925, 2013). "As a cell transforms to a malignant state, MEIS1/2 are epigenetically silenced in more aggressive prostate tumors and expression of tumor-suppressive proteoglycans is suppressed, leading to decreased regulation of oncogenic signaling through pathways such as TGFβ, EGFR, cMYC, WNT, and IGF1R." (PMID 32553107, 2020). "On the other hand, our prior studies show that prostate tumors frequently harbor downregulation of the transcription factors and HOX binding partners MEIS1 and MEIS2 (myeloid ecotropic viral integration site 1/2)." (PMID 32553107, 2020). "In parallel, TGFBR3 (also known as betaglycan) significantly increased with MEIS1 expression (fold-change = 1.67, FDR = 4.13×10−4) and has been shown to inhibit TGFβ signaling and decrease prostate tumor growth and progression in a manner similar to DCN." (PMID 32553107, 2020).
sleep disorder (4 papers, 2020 to 2025). A change from the patient's baseline sleeping pattern, in the hours slept and/or an alteration/dysfunction in the stages of sleep. "We observed 142 associations including at known loci for sleep disorders (e.g. MEIS1, CACNA1C, OLFM4, PAX8 and TCF4)." (PMID 41332830, 2025). "GWAS catalog analysis showed a series of previously reported sleep disorder genes, such as MEIS1, CUL9 and FOXP2 40,44,45." (PMID 32332799, 2020).
Alzheimer disease (3 papers, 2022 to 2025). A progressive, neurodegenerative disease characterized by loss of function and death of nerve cells in several areas of the brain leading to loss of cognitive function such as memory and language. "Additionally, the orthologs of nhr-25(NR5A1 and NR5A2) and unc-62 (MEIS1, MEIS2, MEIS3) were linked to aging-related diseases such as dementia and Alzheimer’s disease." (PMID 40766245, 2025).
bladder cancer (3 papers, 2020 to 2023). "Methylation analysis performed with bladder cancer tissue samples revealed that Meis1 methylation was similar in all of the samples, regardless of the age of the patients." (PMID 33402862, 2020). "A combination of five methylation markers (ONECUT2, MEIS1, OSR1, OTX1, and SIM2) resulted in a bladder cancer prediction model, with a sensitivity of 85% and a specificity of 87%." (PMID 37627900, 2023). "The expression levels of TSHZ3, ISL, MEIS1, ZEB2, and ZFHX4 were significantly lower, whereas the expression of HOXC4 was higher in bladder cancer tissues when compared to that of normal bladder tissues." (PMID 37627900, 2023). "Interestingly, the seven MEIS1 all display DNA hypermethylation in bladder cancer and are negative correlated with MEIS1 expression." (PMID 33659216, 2021). "Therefore, methylation analysis itself is not sufficient for predicting Meis1 function in bladder cancer, and further research is needed." (PMID 33402862, 2020).
gastric cancer (3 papers, 2019 to 2020). A primary or metastatic malignant neoplasm involving the stomach. "Meis1 may function as a tumor suppressor during gastric cancer progression." (PMID 33402862, 2020). "In addition, the overexpression of Meis1 could lead to G1/S cell cycle arrest and cell death of gastric cancer cells." (PMID 33402862, 2020).
melanoma (3 papers, 2010 to 2025). A malignant, usually aggressive tumor composed of atypical, neoplastic melanocytes. "In melanoma cells (namely the MJT1 cell line), MEIS1 and PBX proteins enhance the stability of the HOX-PBX-DNA trimeric complex." (PMID 33402862, 2020).
retinoblastoma (3 papers, 2007 to 2017). A malignant tumor that originates in the nuclear layer of the retina. "To date, tumor suppressors including retinoblastoma and components of the Hippo pathway, as well as Meis1, have been implicated in CM cell-cycle inhibition." (PMID 27768769, 2016). "This is also the first report of the homeodomain gene Meis1 associated with retinoblastoma." (PMID 17615543, 2007).
acute promyelocytic leukemia (2 papers, 2018 to 2022). An aggressive form of acute myeloid leukemia (AML), characterized by arrest of leukocyte differentiation at the promyelocyte stage, due to a specific chromosomal translocation t(15;17) in myeloid cells. "Based on our analysis of the Beat AML dataset, we observe a positive correlation between adverse overall survival and high FLI1 and ELF1 transcript levels in all non-acute promyelocytic leukemia patients, especially in CN-AML where MEIS1 levels are high." (PMID 35624144, 2022).
Anxiety (2 papers, 2016 to 2021). Intense feelings of nervousness, tension, or panic often arise in response to interpersonal stresses. "A study using bioinformatics and transgenic mice approaches indicated the regulatory role of MEIS1 in neuropeptide substance p expression in the amygdala, suggesting a mechanism underlying anxiety and depression." (PMID 34680902, 2021).
cholangiocarcinoma (2 papers, 2018 to 2023). A carcinoma that arises from the intrahepatic biliary tree (intrahepatic cholangiocarcinoma) or from the junction, or adjacent to the junction, of the right and left hepatic ducts (hilar cholangiocarcinoma). "MEIS1 expression in tumor tissues of cholangiocarcinoma (CHOL), Liver hepatocellular carcinoma (LIHC) (p < 0.001) and glioblastoma multiforme (GBM) (p < 0.05) was higher than normal tissues." (PMID 36836180, 2023).
colorectal adenoma (2 papers, 2011 to 2013). An adenoma that arises from the colon or rectum. "In line with our data, a previous study also showed decrease of MEIS1 expression in colorectal adenomas." (PMID 24244575, 2013). "Downregulation of total MEIS1 transcript was observed in colorectal adenomas, suggesting a role for MEIS1 in intestinal tumorigenesis." (PMID 21858198, 2011).
colorectal tumor (2 papers, 2011 to 2013). "Secondly, the association between MEIS1 promoter methylation and BRAFp.V600E as initially found with CpG island microarray analyses was studied in a consecutive series of 228 colorectal tumors consisting of 54% males and an average age of 66 ± 12 years (mean ± SD)." (PMID 24244575, 2013). "MEIS1 promoter methylation status of colorectal tumors and associated fractions." (PMID 24244575, 2013). "To exclude the possibility that the correlation between BRAFp.V600E and MEIS1 promoter methylation is a cohort specific effect, we analyzed an independent consecutive series of 228 colorectal tumors." (PMID 24244575, 2013).
diffuse large B-cell lymphoma (2 papers, 2020 to 2023). "Meis1, Meis2, and Meis3 were upregulated in lymphoid neoplasm diffuse large B-cell lymphoma and thymoma cancers." (PMID 33402862, 2020). "In most cancers, such as lymphoid neoplasm diffuse large B-cell lymphoma (DLBC), PRAD, READ, COAD, OV, KIRC and LIHC, MEIS1 expression was positively related to the expression of most ICPGs." (PMID 36836180, 2023).
endometriosis (2 papers, 2025). The growth of functional endometrial tissue in anatomic sites outside the uterine body. "Our results imply that the loss of MEIS1 in the nucleus may contribute to pathogenesis of endometriosis." (PMID 39934615, 2025). "In conclusion, this study revealed the function of MEIS1 in the pathogenesis of endometriosis, based on its identification in previous genomic studies." (PMID 39934615, 2025). "To investigate the biological function of MEIS1 on endometriosis pathogenesis, we downregulated MEIS1 expression by siRNA in NESCs." (PMID 39934615, 2025). "Upregulation of MEIS1 expression in eutopic stromal cells promoted cell death, consistent with a murine model of endometriosis." (PMID 39934615, 2025). "Consistently, MEIS1 expression was decreased in endometrial stromal cells from endometriosis patients as well as in a mouse model of the disease." (PMID 41374450, 2025). "Herein, we demonstrated that MEIS1 level was decreased in eutopic and endometriotic cells of endometriosis compared with normal endometrium." (PMID 39934615, 2025). "Herein, we identified MEIS1 as an apoptosis-related gene in endometriosis by analyzing our previously published data, RNA-seq and public endometriosis database (GES7305)." (PMID 39934615, 2025). "A higher MEIS1 level induced apoptosis of endometrial stromal cells in endometriosis, in which MEIS1 activated TNFR1 transcription activity to induce the apoptosis caspase pathway." (PMID 39934615, 2025). "The mRNA and protein of MEIS1 in tissues from patients with endometriosis were decreased." (PMID 39934615, 2025). "MEIS1 was overexpressed in cell nucleus and cytoplasm of both epithelial and stromal cells from normal endometrium compared with eutopic endometrium and ectopic endometriotic tissues of endometriosis, especially in stromal cells." (PMID 39934615, 2025). "Our observations established that a mouse model of endometriosis could identify whether MEIS1 treatment had therapeutic effects on endometriosis." (PMID 39934615, 2025). "Using the data from our previous results and RNA sequencing data of normal endometrial tissue and ovarian endometrioma (OMA) tissue, along with Gene Expression Omnibus (GEO) dataset on endometriosis, we identified an apoptotic-related gene, meis homeobox I (MEIS1)." (PMID 39934615, 2025). "Though MEIS1 may be a mediator between sex steroids and key genes for uterine receptivity, its role in the pathogenesis of endometriosis has remained uncertain." (PMID 39934615, 2025). "In short, promoting MEIS1 function may decrease endometriosis progress." (PMID 39934615, 2025). "Our pooling-based GWAS, combined with RNA sequencing and a published endometriosis database (GSE7305), revealed an OMA-related gene—MEIS1." (PMID 39934615, 2025). "Next, MEIS1 protein expression was detected in women with and without endometriosis using Western blotting and immnohistochemistry(IHC)." (PMID 39934615, 2025). "IHC revealed that nuclear and cytoplasmic MEIS1 expression in stromal and glandular cells of endometrial tissues without endometriosis, which are basically the same as Dintilhac’s." (PMID 39934615, 2025). "Targeting MEIS1 may become a future nonhormonal endometriosis therapy alternative." (PMID 39934615, 2025).
erythroleukemia (2 papers, 2021 to 2022). Acute erythroid leukemia characterised by the presence of at least 50% erythroid precursors and at least 20% myeloblasts in the bone marrow. "A recent study has shown that mouse Fli1 promotes chromatin looping between the Meis1 enhancers and promotor in murine erythroleukemia cells." (PMID 35624144, 2022). "In addition to bringing new insights concerning Fli-1 contributions to cancer, our data identify three new enhancers of Meis1 in erythroleukemia." (PMID 33733070, 2021).
esophageal cancer (2 papers, 2020 to 2023). A primary or metastatic malignant neoplasm involving the esophagus. "To deliver shRNA into the esophageal cancer cell line KYSE30, we used a lentiviral-based vector that expressed MEIS1 shRNA." (PMID 32819319, 2020). "In addition, MEIS1 was diversely expressed in multiple molecular subtypes of ACC, BRCA, esophageal carcinoma (ESCA), GBM, HNSC, KIRP, LGG, LIHC, LUSC, ovarian serous cystadenocarcinoma (OV), PCPG, PRAD, STAD and UCEC (all p < 0.05)." (PMID 36836180, 2023).
glioblastoma (2 papers, 2020 to 2023). The most malignant astrocytic tumor (WHO grade IV). "Given the high level of Meis1-2-3 expression in glioblastoma tissues, a study examining the relationship between MEIS1-2-3 and glioblastoma is clearly needed." (PMID 33402862, 2020).
lung adenocarcinoma (2 papers, 2023). A carcinoma that arises from the lung and is characterized by the presence of malignant glandular epithelial cells. "MEIS1 is a hub gene in the differentially expressed gene interaction network for lung adenocarcinoma (LUAD) and participated in the occurrence and prognosis of LUAD." (PMID 36836180, 2023). "MEIS1 (Meis homeobox 1) downregulation is related to lung adenocarcinoma cell proliferation, anchorage-independent growth, cell cycle progress, apoptosis, invasion, and migration." (PMID 36661515, 2023). "The suppression of MEIS1 expression is related with epigenetic regulation mediated by EZH2-DNMT3a and lncRNA ELFN1-AS1, cell viability and tumor growth, and CpG island methylation of squamous cell carcinomas and lung adenocarcinomas cells." (PMID 36661515, 2023).
medulloblastoma (2 papers, 2019 to 2023). A malignant, invasive embryonal neoplasm arising from the cerebellum.
microphthalmia (2 papers, 2010 to 2020). Congenital or developmental anomaly in which the eyeballs are abnormally small. "The MEIS1 gene is the best gap-filling candidate for decoding genetic pathways associated with anophthalmia and microphthalmia." (PMID 32111086, 2020).
myeloid malignancies (2 papers, 2022 to 2024). "Moreover, GATA2 and MEIS1 knockdown in the leukemic cell lines K562 and Kasumi-1 reduced the frequency of CFU-Cs, verifying that GATA2 and MEIS1 could be potential therapeutic targets for ASXL1 mutation–associated myeloid malignancies." (PMID 37917239, 2024).
myeloproliferative disorder (2 papers, 2016 to 2023). A clonal hematopoietic stem cell disorder, characterized by proliferation in the bone marrow of one or more of the myeloid (i.e., granulocytic, erythroid, megakaryocytic, and mast cell) lineages. "This analysis focused on genes (Srpk2, Hes1, Mtor, Pdp1, Meis1, Gfi1, Foxo3, Stra13, Hif1α, and Cebpε) involved in HSC proliferation; maintenance of quiescence, growth, and stem cell exhaustion; and development of myeloproliferative disorder in young and geriatric mice." (PMID 27366154, 2016).
prostate adenocarcinoma (2 papers, 2021 to 2023). "Likewise, amplification became the primary type of MEIS1 gene alteration in ovarian epithelial tumor, bladder urothelial carcinoma, mature B-cell neoplasms and prostate adenocarcinoma." (PMID 36836180, 2023).
squamous cell carcinoma (2 papers, 2021 to 2023). A carcinoma arising from squamous epithelial cells. "MEIS1 might limit the proliferation of non-small-cell lung adenocarcinoma and was described methylated in squamous cell carcinomas." (PMID 34262872, 2021).
thymoma (2 papers, 2020 to 2023). A neoplasm arising from the epithelial cells of the thymus. "This analysis revealed that Meis1-3, Pbx1-3, and Hoxa9 genes are highly upregulated in thymoma when compared to healthy adult tissues." (PMID 33402862, 2020).
adenomyosis (1 paper, 2025). The growth of endometrial tissue inside the muscular wall of the uterine corpus. "Collectively, it can be deduced that MEIS1 may affect implantation difficulties and endometrial proliferations, aligning with the invagination hypothesis for adenomyosis." (PMID 41374450, 2025).